SNHG6 (small nucleolar RNA host gene 6)
Diseases named in the same sentence as SNHG6 in open-access papers (continued):
Sharing a sentence is not in itself a finding about the gene and the disease.
glioma (23 papers, 2019 to 2025). A benign or malignant brain and spinal cord tumor that arises from glial cells (astrocytes, oligodendrocytes, ependymal cells). "SNHG6 association with poor prognosis and low survival is also reported in gliomas." (PMID 37735423, 2023). "Both lncRNA SOX2‐OT and SNHG6 promote glioma progression and cell growth and lncRNA DLEU promotes cell proliferation in glioblastoma." (PMID 39417309, 2025). "The correlation between lncRNAs expression and immunophenotype in glioma, along with the poor survival of glioma patients with reduced SNHG6 expression, were translationally relevant." (PMID 40527978, 2025). "This confirmed the expression of MiR17hg, SNHG6, H19 and Pvt1 in glioma-infiltrating immune cells, consistent with our murine models." (PMID 40527978, 2025). "NCBP3/SNHG6 promotes tumorigenesis in glioma cells by inhibiting the transcription of GBX2 which is a tumor suppressor." (PMID 37735423, 2023). "miR-543 sponging by SNHG6 leads to downstream expression of LAMC1 in breast cancer, while in glioma cells LMO3 gene is activated by binding of SNHG6 to miR-543." (PMID 37735423, 2023). "The study revealed that the knockdown of SNHG6 enhanced the expression levels of miR-543 while the elevated levels of SNHG6 reversed this effect confirming the direct relation of SNHG6 with miR-543 in glioma cells." (PMID 37735423, 2023). "Thereafter, SNHG6 was shown to sponge miR-101 in gastric, glioma, colorectal, non-small cell lung, cholangiocarcinoma, melanoma and esophageal cancer cells." (PMID 36212408, 2022). "SNHG6 was also shown to promote glioma malignant progression by inducing histone modifications in tumor suppressor genes." (PMID 36497269, 2022). "Despite these evidences for a role of SNHG6 in gliomas, its mechanism of action is not fully understood and, therefore, we performed this study to further evaluate the role of SNHG6 in gliomas." (PMID 34485294, 2021). "Our investigation started with an evaluation of the endogenous expression of SNHG6 in some commonly tested glioma cell lines." (PMID 34485294, 2021). "SNHG6 has been shown to affect glioma cell proliferation but its effect on EMT of glioma cells along with its effect on disease progression is not known." (PMID 34485294, 2021). "The levels of SNHG6 and Notch1 were also found elevated in Grade IV glioma patients (n = 4) relative to Grade II glioma patients (n = 5)." (PMID 34485294, 2021). "Our evaluation of these two groups further confirms that SNHG6 as well as Notch1 are elevated in high grade gliomas and are thus verified targets for therapy." (PMID 34485294, 2021). "SNHG6 (small nucleolar RNA host gene 6), located on chromosome 8q13, was identified as an oncogene in several cancers, including gastric cancer, glioma, HCC, and osteosarcoma." (PMID 34247194, 2021). "The four tested glioma cell lines had different levels of SNHG6 with two cell lines, A172 and U87MG expressing high levels of this lncRNA while the remaining two cell lines, H4 and SW088 expressing relatively lower levels of SNHG6." (PMID 34485294, 2021). "In their research, SNHG6 promotes glioma cell proliferation, migration, and EMT and reduces apoptosis by downregulating miR-101-3p." (PMID 32518528, 2020). "Another study carried out by Cai and his team workers detected that upregulated SNHG6 is responsible for glioma cell proliferation, which is consistent with Meng’s results, while silencing SNHG6 can induce cell cycle arrest by upregulating p21." (PMID 32518528, 2020). "SNHG6 regulated the progression of glioma through upregulation of Notch1, Sox2, and EMT." (PMID 38194709, 2024). "SNHG6 also sponges miR-101-3p in glioma to exert its oncogenic influence." (PMID 37735423, 2023). "High expression of SNHG6 has also been reported in gliomas, by other researchers." (PMID 37735423, 2023). "Similarly to DANCR, SNHG6 was shown to promote glioma progression via a similar ceRNA activity by interfering with glioma-relevant miRNAs: miR-543 and miR-101-3p." (PMID 36497269, 2022).
glioma (continued). "Downregulation of SNHG6 in glioma cells has been reported to result in induction of apoptosis." (PMID 34485294, 2021). "One of the relatively less explored lncRNA in gliomas is SNHG6 with just few reports." (PMID 34485294, 2021). "To further explore this relationship and to evaluate whether there is bidirectional regulation, i.e., Notch1 and Sox2 can themselves regulate SNHG6 in glioma cells, we silenced Notch1 and Sox2 using specific siRNAs against them and measured SHHG6 levels." (PMID 34485294, 2021). "Oncogenic roles of SNHG6 were also observed in gastric cancer, glioma, and osteosarcoma." (PMID 30626446, 2019). "A recent study showed that SNHG6 promotes proliferation and EMT in glioma cells by acting as endogenous ceRNA and sponges miR-26a-5p." (PMID 37735423, 2023). "The expression levels of AC062021.1, SNHG6, LINC00507, FAM66C, DGCR10, and LINC00641 were significantly lower in glioma tissues than in normal brain tissues (P < .05) and gradually increased with the degree of malignancy." (PMID 37145002, 2023). "Another reason for investigating EMT was the reported connection between SNHG6 and EMT which has also been reported in gliomas." (PMID 34485294, 2021). "It is interesting to note that we ruled out a reciprocal relationship between Notch1 and SNHG6, at least in our glioma cell line models." (PMID 34485294, 2021). "Also, it needs to be acknowledged that similar to our observations with SNHG6, a number of other lncRNAs have also been reported to regulate EMT in gliomas." (PMID 34485294, 2021). "As a novel lncRNA, SNHG6 had been discovered overexpressed in various types of cancers, including CRC, HCC, breast cancer, gastric cancer, lung cancer, glioma and osteosarcoma." (PMID 32655318, 2020).
gastric cancer (22 papers, 2017 to 2023). A primary or metastatic malignant neoplasm involving the stomach. "It was found that the upregulation of SNHG6 positively influenced B-2 expression by sequestering miR-1297 and the silencing of SNHG6 resulted in the repression of gastric cancer and DDP resistance." (PMID 37735423, 2023). "The levels of SNHG6 and Bcl-2 a known cell death inhibitor expression was found elevated in gastric cancer tissues in comparison to normal tissues." (PMID 37735423, 2023). "SNHG6 suppression in gastric cancer cell lines halted cell growth and attenuated the migratory potential of cells." (PMID 37735423, 2023). "Lastly, again in gastric cancer, lncRNA SNHG6 has been seen to promote cell proliferation and EMT." (PMID 29757368, 2018). "Yang's study found that SNHG6 is overexpressed in gastric cancer tissues and cell lines measured by quantitative real-time polymerase chain reaction (qRT-PCR) and might serve as a candidate prognostic biomarker for gastric cancer patients." (PMID 29254165, 2017).
breast cancer (21 papers, 2017 to 2024). A primary or metastatic malignant neoplasm involving the breast. "MiR-101 was found to attenuate SNHG6-mediated effects on tamoxifen resistance, EMT, and stem cell markers, presenting a crucial role for the SNHG6-miR-101 axis in tamoxifen resistance of ER-positive breast cancer cells." (PMID 39439957, 2024). "Using bioinformatics tools and wet lab experiments it was found that SNHG6 directly binds with miR-543 which has been previously identified as a tumor suppressor in ovarian and breast cancer." (PMID 37735423, 2023). "Despite their effort, more questions regarding SNHG6 differential expression in other breast cancer types: HER2 ±, Estrogen ±, and triple-negative rise." (PMID 37735423, 2023). "According to them, SNHG6-203 expression is up-regulated in high-stage breast cancer than the low-stage." (PMID 37735423, 2023). "We now provide first evidence for a role of lncRNA SNHG6 in drug resistance of breast cancer, in general, and tamoxifen resistance, in particular." (PMID 36212408, 2022). "Small nucleolar RNA host gene 6 (SNHG6) is significantly overexpressed in breast cancer (BC) cells and tissues compared to normal cells." (PMID 36294743, 2022). "We found that SNHG6 expressions appeared to be raised in samples of breast cancer in contrast to healthy breast tissue samples." (PMID 34026654, 2021). "For instance, SNHG6 facilitated cancer cell migration and proliferation in ovarian clear cell cancer, breast cancer, and lung adenocarcinoma." (PMID 32782439, 2020). "miR-26a-5p/ULK1 and miR-26a-5p/MAPK6 axis were also regulated by SNHG6 and participated in the development and progression of breast cancer and osteosarcoma, respectively." (PMID 32655318, 2020). "LncRNA PVT1 was lower in grade I and III breast cancers, and SNHG6 was upregulated in grade I breast cancer." (PMID 28938549, 2017). "SNHG6 serving as an endogenous sponge inhibits miR-26a and miR-26a-5p in breast cancer." (PMID 37735423, 2023). "The carcinogenic role of SNHG6 is also explored in breast cancer." (PMID 37735423, 2023). "Studies demonstrating SNHG6 expression differences in all breast cancer types and also describing expression differences among each type could better facilitate understanding its role as a prognostic and diagnostic marker." (PMID 37735423, 2023). "The increased levels of both SNHG6 and LAMC1 are associated with poor prognosis in breast cancer." (PMID 37735423, 2023). "However, our work is the first to demonstrate induction of EMT by SNHG6 in breast cancer cells with functional implications in acquired resistance against tamoxifen." (PMID 36212408, 2022). "SNHG6 may contribute to breast cancer aggressiveness via the miR-26a/VASP axis." (PMID 38948025, 2024). "Even though a role of SNHG6 in cancer radio-resistance as well as chemoresistance, particularly resistance against cisplatin and paclitaxel has been described, there is no report on it’s possible role in acquired tamoxifen resistance of ER-positive breast cancers, prompting us to plan this study." (PMID 36212408, 2022). "SNHG6 promoted EMT and migration in breast cancer cells by sequestering miR-543 and hence elevating the expression of LAMC1, which is a target of miR-543." (PMID 37735423, 2023). "It was shown that patients had lower five years survival rate in breast cancer with alteration in PVT1 and SNHG6." (PMID 28938549, 2017). "The results showed that SNHG6 and NEAT1 were reversely expressed in breast cancer combined with primary lung cancer compared with primary breast or lung cancer." (PMID 28938549, 2017). "AHIF, MALAT1, SNHG6, UCA1 expression levels increased in breast cancer tissues compared with their counterpart adjacent tissues, while AFAP1-AS1, PVT1, HYMAI had lower expression in tumors." (PMID 28938549, 2017). "The results demonstrated that SNHG6 and NEAT1 had opposite change of expression levels in breast cancer combined with primary lung cancer patients." (PMID 28938549, 2017).
breast cancer (continued). "In this study, we selected four lncRNAs which had expression alterations ranging from 12% to 20% in breast carcinoma, including PVT1, linc00467, SNHG6, linc00657." (PMID 28938549, 2017). "Silencing SNHG6 sensitizes resistant cells to tamoxifen, reverses EMT, and reduces invasion and clonogenicity, implicating the SNHG6-miR-101 axis as a potential target for overcoming tamoxifen resistance in breast cancer." (PMID 39439957, 2024). "Further, miR-101 was found to attenuate SNHG6-mediated effects on tamoxifen resistance, EMT as well as stem cell markers, thereby making a case for SNHG6-miR-101 axis in tamoxifen resistance of ER-positive breast cancer cells." (PMID 36212408, 2022). "Overexpression of SNHG6 could promote cell cycle progression, proliferation, migration, and EMT of breast cancer cells." (PMID 33330110, 2020). "The findings revealed that PVT1, SNHG6, NEAT1 may serve as a prognostic marker for breast cancer combined with primary lung cancer." (PMID 28938549, 2017). "The data indicated that SNHG6 might be related to pathogenesis and early diagnosis of breast carcinoma, and PVT1 was likely to inhibit breast cancer aggressiveness." (PMID 28938549, 2017). "While our present report is the first one to demonstrate sponging of miR-101 by SNHG6 in breast cancer, particularly in tamoxifen-resistant breast cancer, there is ample evidence from other cancer as well as non-cancer models to confirm such miR-101 sponging by SNHG6." (PMID 36212408, 2022).
osteosarcoma (19 papers, 2019 to 2024). A usually aggressive malignant bone-forming mesenchymal neoplasm, predominantly affecting adolescents and young adults. "In our study, SNHG6 as a risk molecule was negatively associated with the outcome of osteosarcoma patients and was highly expressed in the high FRL-score group." (PMID 35837104, 2022). "Meanwhile, SNHG6 expression is increased in osteosarcoma and is a new risk prognostic biomarker for osteosarcoma." (PMID 36568384, 2022). "In osteosarcoma, SNHG6 is associated with advanced stages of cancer and poor survival." (PMID 37735423, 2023). "In consequence, we explored the biological behavior of SNHG6 by constructing the osteosarcoma cell model, and the results show that SNHG6 regulates the progression of osteosarcoma cells." (PMID 38194709, 2024). "After SNHG6 knockdown, the migration and invasion capacities of osteosarcoma cells were markedly reduced according to the results (*** P < 0.001)." (PMID 38194709, 2024). "Surprisingly, attenuation of SNHG6 in osteosarcoma cells reduced the expression of AXL and p-AXL, and WB results showed that the phosphorylation of AKT was also affected (** P < 0.01)." (PMID 38194709, 2024). "In order to further investigate the impact of SNHG6 on the migration and invasion of osteosarcoma cells, we performed transwell assay." (PMID 38194709, 2024). "SNHG6 was found to be overexpressed in osteosarcoma cells and tissues, and its high expression was correlated with poor survival and metastasis." (PMID 36899946, 2023). "It has been documented that SNHG6 was up regulated in osteosarcoma tissues that was correlated with tumor grade and shorter overall survival." (PMID 37807067, 2023). "SNHG6 knockdown osteosarcoma cells show reduced proliferation, migration, and invasion indicating a strong relation between SNHG6 expression and tumorigenesis as well as metastasis." (PMID 37735423, 2023). "Increased expression of SNHG6 in cells is correlated with the poor prognosis of osteosarcoma patients." (PMID 37735423, 2023). "The SNHG6-mediated autophagy induces the pro-tumor effects in osteosarcoma that are further confirmed by silencing the SNHG6 and disrupting the miR-26a-5p/UKL1 pathways showing anti-tumor effects in osteosarcoma cells." (PMID 37735423, 2023). "Another study also showed that SNHG6 inhibits autophagy and apoptosis but promotes metastasis in osteosarcoma via the miR-26a-5p/ULK1 axis." (PMID 35837104, 2022). "Silencing of SNHG6 suppressed cell proliferation and invasion, and induced autophagy in osteosarcoma cells, possibly by sponging miR-26a-5p to restore the expression of its target ULK1." (PMID 33050642, 2020). "Serval lncRNAs were found to be associated with cancer metastasis and advanced TNM stage, such as HCG11 and MCM3AP-AS in HCC, and SNHG6 in osteosarcoma." (PMID 33050642, 2020). "In summary, we have newly identified the SNHG6/miR-26a-5p/ULK1 regulatory mechanism of autophagy in human osteosarcoma, and provided an optional choose for human OS treatment in the future." (PMID 30988663, 2019). "In this study, we found that SNHG6 is able to promote CRC chemoresistance and enhance autophagy through regulation of ULK1 by sponging miR-26a-5p, which has been confirmed to be regulated by SNHG6 to suppress osteosarcoma." (PMID 31516391, 2019). "SNHG6 facilitated the osteosarcoma cell proliferation via p21 and KLF2 modulations." (PMID 37807067, 2023). "Moreover, SNHG6 silencing decreased proliferation, migration, and autophagy and induced G0/G1 phase arrest and apoptosis in osteosarcoma." (PMID 36899946, 2023). "Here we investigated how SNHG6 effected human osteosarcoma (OS) development and progression." (PMID 30988663, 2019). "SNHG6 might serve as a candidate prognostic biomarker and a target for novel therapies of osteosarcoma patients." (PMID 30988663, 2019). "Therefore, SNHG6 may regulate the proliferation, migration, and invasion of osteosarcoma cells through AXL." (PMID 38194709, 2024).
osteosarcoma (continued). "Thus, SNHG6 is involved in osteosarcoma progression and may serve as an oncogene." (PMID 32518528, 2020). "High expression of AP000943.1, AC015795.1, AC016746.1, LINC01976, and SNHG6 was not conducive to the prognosis of osteosarcoma." (PMID 34692688, 2021).
lung adenocarcinoma (9 papers, 2019 to 2025). A carcinoma that arises from the lung and is characterized by the presence of malignant glandular epithelial cells. "In lung adenocarcinoma cells, SNHG6 sponges miR-26a-5p and regulate E2F7 expression leading to the attainment of cell motility and EMT properties." (PMID 37735423, 2023). "SNHG6, which has been reported in literature to inversely correlate with macrophages, neutrophils, and dendritic cells (DCs) infiltration in lung adenocarcinoma, was unexpectedly upregulated in microglia, BAMs, GAMs, and macrophages, but was downregulated in NK cells." (PMID 40527978, 2025).
lung cancer (7 papers, 2017 to 2023). A malignant neoplasm involving the lung. "In lung cancer, SNHG6 promotes ETS1 signaling by targeting its inhibitor microRNAs: miR-944 and miR-181d-5p." (PMID 37735423, 2023). "SPI1-induced upregulation of lncRNA SNHG6 promotes nonsmall-cell lung cancer via miR-485-3p/VPS45 axis." (PMID 36967718, 2023). "To summarize, the authors demonstrated that SNHG6 were involved in progression of lung cancer by regulating multiple miRNAs, representing promising targeted therapeutic strategies against NSCLC." (PMID 32518528, 2020).
prostate carcinoma (7 papers, 2020 to 2024). A carcinoma that arises from epithelial cells of the prostate gland. "Experimentally and clinically, the suppression of SNHG6 led to an increase in the susceptibility of PTX-resistant prostate cancer cells to the drug." (PMID 39512820, 2024). "Expression of the lncRNA small nucleolar RNA host gene 6 (SNHG6) is associated with decreased miR-186 in PTX-resistant prostate cancer cells and patient tissues." (PMID 33182737, 2020). "While in prostate cancer cells resistant to paclitaxel, increased SNHG6 expression leads to inhibition of miR-186 activity which is believed to be the cause of drug resistance and cell proliferation." (PMID 37735423, 2023). "The silencing of SNHG6 not only decreased cell proliferation, invasion, and migration, but also elevated the sensitivity of prostate cancer tissues to paclitaxel (PTX) confirming the role of SNHG6 in PTX resistance." (PMID 37735423, 2023). "They found that levels of SNHG6 were highly increased while miR-186 was found to be downregulated in drug-resistant prostate cancer tissues." (PMID 37735423, 2023). "It has been suggested that SNHG6 may have the potential to be a therapeutic factor for prostate cancer." (PMID 39512820, 2024).